RNU7-14P (RNA, U7 small nuclear 14 pseudogene)
Synonyms: U7.14
Gene: Small nuclear RNA gene on chromosome 20 (53,668,697 to 53,668,758, reverse strand). Ensembl gene ENSG00000238468.
Homologues: Orthologues: macaque U7 (85% identical). Paralogues in human: RNU7-7P (92% identical), RNU7-23P (90% identical), RNU7-28P (90% identical), RNU7-3P (90% identical), RNU7-40P (90% identical), RNU7-4P (90% identical), RNU7-11P (89% identical), RNU7-128P (89% identical), RNU7-18P (89% identical), RNU7-21P (89% identical), RNU7-27P (89% identical), RNU7-34P (89% identical), and 141 more.